ZC3H13 (zinc finger CCCH-type containing 13)
Description:
Associated component of the WMM complex, a complex that mediates N6-methyladenosine (m6A) methylation of RNAs, a modification that plays a role in the efficiency of mRNA splicing and RNA processing. Acts as a key regulator of m6A methylation by promoting m6A methylation of mRNAs at the 3'-UTR (By similarity). Controls embryonic stem cells (ESCs) pluripotency via its role in m6A methylation (By similarity). In the WMM complex, anchors component of the MACOM subcomplex in the nucleus (By similarity). Also required for bridging WTAP to the RNA-binding component RBM15 (RBM15 or RBM15B) (By similarity).
Synonyms: KIAA0853; DKFZp434D1812; Xio
Tractability: PROTAC: UniProt records ubiquitination sites on it; ubiquitination databases record sites on it; its protein half-life has been measured.
Gene: Protein-coding gene on chromosome 13 (45,954,364 to 46,052,781, reverse strand). Ensembl gene ENSG00000123200.
Subcellular location: Nucleus speckle; Nucleus, nucleoplasm
Subcellular location (Human Protein Atlas): Nucleoplasm
Gene Ontology:
Molecular function: protein binding; RNA binding; metal ion binding
Biological process: mRNA processing; regulation of stem cell population maintenance
Cellular component: nuclear speck; nucleoplasm; RNA N6-methyladenosine methyltransferase complex; nucleus
Genetic constraint (gnomAD): Loss-of-function variants: 59 observed, 194.81 expected, observed/expected ratio (o/e) 0.3, 90% interval 0.25 to 0.38. The upper end of that interval is the gene's LOEUF score, 0.38, which puts it in group 1 of 6, group 1 being the genes least tolerant of losing a copy. Missense variants: 1,779 observed, 2,106.7 expected, observed/expected ratio (o/e) 0.84, 90% interval 0.81 to 0.88. Synonymous variants: 648 observed, 701.57 expected, observed/expected ratio (o/e) 0.92, 90% interval 0.87 to 0.99.
Homologues: Orthologues: chimpanzee ZC3H13 (99% identical), macaque ZC3H13 (98% identical), dog ZC3H13 (93% identical), rabbit ZC3H13 (92% identical), pig ZC3H13 (90% identical), guinea pig ZC3H13 (90% identical), mouse Zc3h13 (86% identical), rat Zc3h13 (86% identical), tropical clawed frog zc3h13 (61% identical), zebrafish zc3h13 (51% identical).
Diseases named in the same sentence as ZC3H13 in open-access papers:
ZC3H13 is named in the same sentence as 68 diseases in open-access papers, as found by Europe PMC text mining. Sharing a sentence is not in itself a finding about the gene and the disease. The quoted sentences say what the papers report.
colorectal cancer (22 papers, 2020 to 2025). A primary or metastatic malignant neoplasm that affects the colon or rectum. "ZC3H13 (zinc finger CCCH-type containing 13) is a canonical zinc finger protein, which harbors a somatic frame-shift mutation in colorectal cancer." (PMID 39457524, 2024). "Low expression of ZC3H13 was associated with the progression of colorectal cancer by inactivating Ras-ERK signaling pathway." (PMID 32038982, 2020). "In contrast, some studies suggest that ZC3H13 is a tumor suppressor gene for colorectal cancer and breast cancer." (PMID 40774945, 2025). "Accumulated investigation have found that ZC3H13 is lowly expressed in different tumors such as hepatocellular, thyroid, colorectal carcinoma, inhibit the occurrence and development of tumor." (PMID 38351022, 2024). "Among them, ZC3H13 was highly expressed in five cancers, including colorectal cancer, kidney cancer, lymphoma, melanoma and sarcoma." (PMID 35278064, 2022). "In breast cancer and colorectal cancer, ZC3H13 plays a tumor suppressive role, while in hepatocellular carcinoma, ZC3H13 promotes the malignant behavior of hepatocellular carcinoma cells." (PMID 36712973, 2022). "ZC3H13 can inhibit the proliferation and invasion of colorectal cancer and regulate the self-renewal of mouse embryonic stem cells." (PMID 35281840, 2022). "The expression of ZC3H13 is up-regulated in patients with colorectal cancer, kidney cancer, melanoma and sarcoma." (PMID 35582419, 2022). "ZC3H13 works as a cancer inhibitory factor in colorectal cancer, but another study indicated that ZC3H13 functions as an oncogene in several types of cancers." (PMID 34248650, 2021). "A report shows that ZC3H13 serves as a tumor suppressor protein in colon carcinoma and colorectal cancer by regulating the Ras-ERK signaling pathway." (PMID 32903675, 2020). "ZC3H13 has also been reported to act as a tumor suppressor in breast and colorectal cancer." (PMID 36581816, 2022). "In colorectal cancer, ZC3H13 acting as a tumor suppressor could suppress cancel cells proliferation and invasion via inactivating Ras-ERK signaling pathway." (PMID 34804925, 2021). "ZC3H13 could suppress proliferation and invasion in colorectal cancer and regulate mouse embryonic stem cell self-renewal." (PMID 33134160, 2020). "Similar to other tumors, the regulation of m6A modifications in colorectal cancer is equally diverse and complex, and almost all m6A modifiers except METTL14, ZC3H13, METTL3, FTO, ALKBH5, and YTHDF2 promote colorectal carcinogenesis." (PMID 39967906, 2025). "ZC3H13 (zinc finger CCCH domain‐containing protein 13), a classical CCCH zinc finger protein, inhibits proliferation and invasion of colorectal cancer cells via blocking the Ras-ERK signaling pathway." (PMID 34312475, 2021). "In addition, ZC3H13 suppresses proliferation and invasion by inactivating Ras-ERK signaling in colorectal cancer." (PMID 34531875, 2021). "It was reported that the downregulation of ZC3H13 expression regulated KRAS and ERK signaling expression, which could inhibit the invasion and proliferation of colorectal cancer cells." (PMID 32733931, 2020).
breast carcinoma (20 papers, 2020 to 2025). "Association between mRNA expression of METTL14, ZC3H13 and clinicopathological characteristics in breast cancer patients (TCGA)." (PMID 33363011, 2020). "Reduced activity of METTL14 and ZC3H13 methyltransferases correlates with lower survival and acts as a tumor-suppressive in breast cancer." (PMID 41157107, 2025). "It has been reported that METTL14 and ZC3H13 act as tumour suppressor genes and predict poor prognosis in breast cancer." (PMID 36567510, 2023). "The downregulation of ZC3H13 expression in breast cancer patients coincides with the fact that this downregulation promotes breast cancer invasion." (PMID 35278064, 2022). "Another study based on bioinformatics suggests that the low expression of METTL14 and ZC3H13 mRNA indicates a poor prognosis of breast cancer." (PMID 33777035, 2021). "The expression of METTL14 and ZC3H13 in breast cancer was positively correlated with the infiltration of CD4+T cells, CD8+T cells, neutrophils, macrophages and DC, and negatively correlated with Treg cells." (PMID 33777035, 2021). "This study demonstrated that down-regulation of METTL14 and ZC3H13 which act as two tumor suppressor genes was found in breast cancer and predicted poor prognosis." (PMID 33363011, 2020). "Breast Cancer Gene-Expression Miner v4.5 showed that LRPPRC level was negatively associated with ER and PR expression, while METTL16, RBM15B, ZC3H13 level was positively linked with ER and PR expression." (PMID 33362863, 2020). "Low expression of METTL14 and ZC3H13 was related to breast cancer progression (increased SBR grade status and NPI classification) and was significantly decreased in ER-, PR- and basal-like, TNBC patients." (PMID 33363011, 2020). "This indicated that low expression of METTL14 and ZC3H13 promoted immunosuppression in the breast cancer, which is also an important downstream mechanism for their role in the progression and metastasis of breast cancer." (PMID 33363011, 2020). "In order to explore the roles of METTL14 and ZC3H13 in the survival of breast cancer patients, the Kaplan–Meier plotter was used to calculate the correlation between the mRNA expression levels and survival." (PMID 33363011, 2020). "The results showed that METTL14 and ZC3H13 were the down-regulated m6A methylation transferases in breast cancer." (PMID 33363011, 2020). "We evaluated the genomic alteration of METTL14 and ZC3H13 among breast cancer samples by the cBioPortal online database (TCGA, PanCancer Atlas)." (PMID 33363011, 2020). "In total, we highlighted the important role of METTL14 and ZC3H13 in breast cancer, provided promising markers for predicting prognosis of patients, and explained the potential molecular mechanism of the two as tumor suppressor genes." (PMID 33363011, 2020). "After excluding cases with incomplete clinical data of TCGA breast cancer patients from UCSC Xena, 637 cases were included to analyzed the association of METTL14 and ZC3H13 expression with clinical and pathological features through chi-squared test." (PMID 33363011, 2020). "In conclusion, our study revealed that METTL14 and ZC3H13, as two tumor suppressor genes, were down-regulated in breast cancer, and the low expression of METTL14 and ZC3H13 was negatively correlated with the OS and RFS." (PMID 33363011, 2020). "The methyltransferase ZC3H13 has also been reported to play a role in the progression of a variety of cancers, including cervical, colorectal, pancreatic, hepatocellular, thyroid and breast cancer." (PMID 40774945, 2025). "However, previous research has found that ZC3H13 acts as a tumor suppressor gene in breast carcinoma." (PMID 36016585, 2022). "Immune infiltration analysis indicated that METTL14 and ZC3H13 could facilitate breast cancer invasion by influencing immunosuppression-related pathways." (PMID 36261786, 2022). "In addition, ZC3H13 levels are also positively correlated with ER and PR expression in breast cancer." (PMID 35223847, 2022).
breast carcinoma (continued). "ZC3H13 was also found to be Tumor Suppressor Genes in Breast Cancer." (PMID 34187307, 2021). "Besides, we also calculated the association between immune infiltrates and somatic CNV of METTL14 and ZC3H13 in breast cancer, and these immune cells showed diverse enrichment trends in different CNV types across different types of breast cancer." (PMID 33363011, 2020). "The results in breast cancer patients showed that the relatively high expression of YTHDF3 and LRPPRC were remarkably associated with worse RFS, whereas relatively high expression of RBM15B, ZC3H13, and METTL16 had better RFS." (PMID 33362863, 2020). "In this study, we used a series of bioinformatic databases and tools to jointly analyze the expression of m6A methylation transferases (METTL3, METTL14, WTAP, RBM15, RBM15B and ZC3H13) and investigate the prognostic value of METTL14 and ZC3H13 in breast cancer." (PMID 33363011, 2020). "Survival outcome analysis suggested that abnormally low expression of METTL14 and ZC3H13 could predict unfavorable prognosis in four breast cancer subtypes." (PMID 33363011, 2020). "Based on the correlation of APC and METTL14, ZC3H13 in breast cancer, we speculated that METTL14 and ZC3H13 were indirectly involved in mediating tumor immune responses." (PMID 33363011, 2020). "However, since the expressions of METTL14 and ZC3H13 in breast cancer were significantly reduced, this process is reversed, resulting in a decrease in the stability of APC mRNA and inhibiting the protein level of APC." (PMID 33363011, 2020). "What is more, survival analysis showed that low METTL14 and ZC3H13 expression could demonstrate poor prognosis in breast cancer for OS and RFS." (PMID 33363011, 2020). "In breast cancer, METTL14 and ZC3H13 were down-regulated, indicating a positive correlation between the expression of METTL14 and ZC3H13 positively correlated with various kinds of immune cells, including macrophages, T cells and DCs." (PMID 38637813, 2024). "In breast cancer, eight genes (METTL3, KIAA1429, ZC3H13, FTO, YTHDF1, YTHDF2, IGF2BP2, and IGF2BP3) were significantly enriched in tumor cells compared to immune or stromal cells." (PMID 35794212, 2022). "For instance, the expression of METTL14 and ZC3H13 is positively correlated with infiltrating levels of CD4+ T cells, CD8+ T cells, and DCs, but negatively correlated with those of Tregs in breast cancer." (PMID 34616742, 2021). "From another perspective, Kaplan-Meier Plotter platform showed that the relatively high expression of YTHDF3 and LRPPRC and the relatively low expression of RBM15B, ZC3H13, and METTL16 in breast cancer patients had worse Relapse-Free Survival (RFS)." (PMID 33362863, 2020). "According to the clinical database of breast cancer of TCGA, RBM15B, YTHDF3, ZC3H13, METTL16, and LRPPRC were picked up indicating strong associations with clinical characteristics." (PMID 33362863, 2020). "In HER-2 (+) breast cancer patients, LRPPRC, METTL16, RBM15B, and ZC3H13 expressed lower than the HER-2 (−)." (PMID 33362863, 2020). "In HER-2 (+) breast cancer patients, the expression of LRPPRC, METTL16, RBM15B, and ZC3H13 were all lower than the HER-2 (−) group." (PMID 33362863, 2020). "To further elucidate the downstream molecular mechanism involved in METTL14 and ZC3H13 by regulating m6A in breast cancer, we selected a set of 76 common positively co-expressed genes of METTL14 and ZC3H13." (PMID 33363011, 2020). "METTL3, METTL16, ZC3H13, YTHDC1 and FTO were expressed at a low level in breast cancer, while KIAA1429, RBM15, and YTHDF1 were expressed at a high level." (PMID 33362863, 2020). "The high expression of YTHDF3, ZC3H13, LRPPRC, and METTL16 indicated poor survival rate in patients with breast cancer, while high expression of RBM15B pointed to a better survival rate." (PMID 33362863, 2020). "Survival analysis of METTL14, ZC3H13 and APC in breast cancer patients (the PrognoScan)." (PMID 33363011, 2020).
breast carcinoma (continued). "Furthermore, mining of TIMER database based on TCGA breast cancer samples demonstrated that only the mRNA expression levels of METTL14 and ZC3H13 were also lower in tumor samples, and there was not any difference of METTL3 and RBM15B." (PMID 33363011, 2020). "In this study, we used Oncomine and The Cancer Genome Atlas (TCGA) databases to jointly analyze the expression of m6A “writer” in breast cancer including METTL3, METTL14, WTAP, RBM15, RBM15B, and ZC3H13, indicating that the mRNA expression levels of METTL14 and ZC3H13 were lower in tumor samples." (PMID 33363011, 2020). "The expression of METTL3, METTL14, RBM15B, and ZC3H13, but not of WTAP and RBM15, was significantly decreased in breast cancer." (PMID 33363011, 2020). "METTL14, ZC3H13, and APC expression levels had significant positive correlation with infiltrating levels of CD4+ T cells, CD8+ T cells, neutrophils, macrophages, and dendritic cells, and negative correlation with Treg cells in breast cancer." (PMID 33363011, 2020).
cervical cancer (9 papers, 2022 to 2025). A primary or metastatic malignant neoplasm involving the cervix. "Bioinformatics analysis of public cancer datasets revealed firm links between m6A modification patterns and cervical cancer prognosis, especially through ZC3H13-mediated m6A modification of CENPK mRNA." (PMID 35418160, 2022). "Meanwhile, we detected that mRNA of key prognostic genes TXNDC12 and ZC3H13 were highly expressed in cervical cancer cells by RT-qPCR." (PMID 36712973, 2022). "The IHC analysis showed that ZC3H13 was localized in the nucleus and had a low expression in cervical cancer tissues." (PMID 36058934, 2022). "PD-L1 expression increased dramatically in cervical cancer tissues and was significantly linked to ALKBH5, FTO, METTL3, RBM15B, YTHDF1, YTHDF3, and ZC3H13 expression levels." (PMID 36091006, 2022). "We used qPCR to study ZC3H13 expression in ten normal cervical tissues and ten cervical cancer tissues and found that ZC3H13 was significantly downregulated in cervical cancer tissues." (PMID 36058934, 2022). "Three m6A regulators (METTL16, YTHDF1, and ZC3H13) were chosen as the minimum standard for constructing a predictive signature, and the riskscore of each cervical cancer patient was determined." (PMID 36091006, 2022). "Our study showed that knocking down ZC3H13, an m6A methyltransferase, can promote the proliferation, migration, and invasion abilities of cervical cancer cells and reduce the m6A levels." (PMID 36058934, 2022). "The prognostic signature-based riskscore (METTL16, YTHDF1, and ZC3H13) was found to be an independent prognostic indicator of cervical cancer." (PMID 36091006, 2022). "Subsequently, we studied the expression and function of ZC3H13 in cervical cancer tissues according to the screening results." (PMID 36058934, 2022). "Our findings further illustrated how ZC3H13 functions in promoting the tumorigenic properties of cervical cancer cells via CENPK." (PMID 35418160, 2022). "This study indicated that METTL16, YTHDF1, and ZC3H13 could regulate the expression of PD-L1 in cervical cancer." (PMID 36091006, 2022). "Furthermore, this study created a three-gene prognostic marker consisting of an m6A methylation regulatory factor, namely, METTL16, YTHDF1, and ZC3H13, and the calculated riskscore had a good predictive effect on cervical cancer patients." (PMID 36091006, 2022). "Because CENPK has a potential oncogenic role in cervical cancer, we speculated that ZC3H13 might be responsible for m6A methylation of CENPK mRNA." (PMID 35418160, 2022). "The WB analysis also demonstrated the low expression of ZC3H13 in cervical cancer tissues." (PMID 36058934, 2022). "We revealed higher levels of ZC3H13, WTAP, HNRNPC, YTHDF3, and VIRMA were significantly associated with worse outcomes in CESC (HR > 1, blue background), while YTHDC1, YTHDF1 were protective factors of cervical cancer (HR < 1, orange background)." (PMID 35581263, 2022). "Moreover, downregulation of METTL16, YTHDF1, or ZC3H13 in two cervical cancer cell lines elevated the expression of PD-L1." (PMID 36091006, 2022). "However, the relevance of METTL16 and ZC3H13 in cervical cancer is still not fully known." (PMID 36091006, 2022).